CIMAP1D (CIMAP1 family member D)
Synonyms: C19orf19; ODF3L2; FLJ40059
Tractability: No criterion of Open Targets' tractability assessment is met for any kind of drug.
Gene: Protein-coding gene on chromosome 19 (463,346 to 474,983, reverse strand). Ensembl gene ENSG00000181781.
Subcellular location (Human Protein Atlas): Flagellar centriole; Mid piece; Nucleoli; Principal piece
Gene Ontology:
Molecular function: protein binding
Cellular component: cytoplasmic microtubule; cytoskeleton
Genetic constraint (gnomAD): Loss-of-function variants: 7 observed, 4.37 expected, observed/expected ratio (o/e) 1.6, 90% interval 0.83 to 1.94. That is too few expected variants to judge how well the gene tolerates losing a copy. Missense variants: 400 observed, 335.86 expected, observed/expected ratio (o/e) 1.19, 90% interval 1.1 to 1.29. Synonymous variants: 184 observed, 146.26 expected, observed/expected ratio (o/e) 1.26, 90% interval 1.12 to 1.42.
Homologues: Orthologues: macaque CIMAP1D (96% identical), pig CIMAP1D (79% identical), mouse Cimap1d (79% identical), rat Cimap1d (78% identical), dog CIMAP1D (74% identical), zebrafish cimap1d (39% identical), zebrafish odf3l2a (38% identical), tropical clawed frog cimap1c (35% identical). Paralogues in human: CIMAP1C (32% identical), CIMAP1A (30% identical), CIMAP1B (29% identical), STPG2 (17% identical), STPG1 (13% identical).
Diseases named in the same sentence as CIMAP1D in open-access papers:
CIMAP1D is named in the same sentence as 12 diseases in open-access papers, as found by Europe PMC text mining. Sharing a sentence is not in itself a finding about the gene and the disease.
CIMAP1D shares sentences with these, for which no sentence is quoted: bladder cancer (1 paper); breast carcinoma (1); cancer (1); colorectal cancer (1); deafness (1); hearing loss (1); liver cancer (1); lung carcinoma (1); melanoma (1); thyroid cancer (1); tumor (1); type 1 diabetes mellitus (1).